MANF (mesencephalic astrocyte derived neurotrophic factor)
Diseases named in the same sentence as MANF in open-access papers (continued):
Sharing a sentence is not in itself a finding about the gene and the disease.
Stroke (continued). "When exogenous MANF is administered into the brain via a viral vector or as a recombinant protein before or a few hours after stroke, it has neuroprotective effects on ischemic stroke models." (PMID 35783104, 2022). "MANF facilitates the differentiation and migration of neural progenitor cells and thus increasing neuroblast recruitment in stroke cortex." (PMID 33738280, 2021). "This is in line with the study performed in stroke cortex and that describes the neuroregenerative activity of MANF through its capacity to favor differentiation and migration of neural progenitor cells." (PMID 33738280, 2021). "Intracerebral delivery of recombinant human MANF protein (rhMANF) or rAAV-mediated MANF gene also reduces cerebral infarction and neuronal cell apoptosis in stroke animals." (PMID 30760285, 2019). "In both cases, the neuroprotection was observed with hastened behavioral recovery over the two-week time period after stroke, indicating not only neuroprotection, but also that MANF has beneficial effects post-stroke." (PMID 31044581, 2019). "Taken together, these studies indicate that MANF promotes brain recovery after stroke via a mechanism that has both immunomodulatory and neuroregenerative effects in the stroke brain." (PMID 31044581, 2019). "Intracerebral injection of purified MANF reduces the volume of infarction and improves behavior recovery in a rat stroke model." (PMID 29687079, 2018). "Pretreatment and treatment after ischemic injury with MANF significantly reduced the ischemia brain injury and improved the behavior in stroke rats." (PMID 27608005, 2016). "The emphasis on human stroke brain samples is crucial as it not only provides a clinically relevant perspective but allows identifying potential species-specific differences in MANF protein expression, which need to be taken into account for translational research and therapeutic development." (PMID 38229173, 2024). "To evaluate whether MANF expression post-stroke is similar in rat as we have found in the human brain, we next characterized MANF protein immunostaining patterns in a rat model of dMCAo at 2, 7, 14, 28, 56, and 112 days post-stroke (n = 4 per time point)." (PMID 38229173, 2024). "However, in the 2 weeks post-stroke samples, high numbers of MANF and CD68 positive round cells were detected in the infarct region." (PMID 38229173, 2024). "MANF expression in the ischemic area of 1-week post-stroke samples was very low." (PMID 38229173, 2024). "However, after stroke, there is a drastic change in this, and brain microglia/macrophages express robustly MANF protein." (PMID 38229173, 2024). "Given the functions of RNF2 in promoting the stabilization of MANF via monoubiquitination, we inferred that RNF2 might facilitate MANF nuclear translocation under stroke stress." (PMID 39614674, 2024). "Additionally, in stroke and traumatic brain injury models, intracranial MANF treatment has been shown to decrease brain edema and BBB leakage." (PMID 38229173, 2024). "It would be highly interesting to generate a mouse line with microglia/macrophage specific MANF deletion and study whether the recovery from stroke is hindered in these mice compared to wild type." (PMID 38229173, 2024). "In fact, limited MANF immunoreactivity was observed at day 3 and at 1-week post-stroke." (PMID 38229173, 2024). "In addition, we have previously shown that NestinCre/+::Manffl/fl mice have increased lesion volume 2 days after stroke, indicating that endogenous neuronal MANF is neuroprotective." (PMID 38229173, 2024). "The administration of recombinant forms of cerebral dopamine neurotrophic factor (CDNF) or MANF post-stroke has been shown to enhance recovery of neurological function, presenting a promising therapeutic strategy for addressing stroke-induced limb dysfunctions." (PMID 38377025, 2024).
Stroke (continued). "Intravenous recombinant MANF treatment decreased the levels of pro-inflammatory cytokines and increased the levels of anti-inflammatory cytokine IL-10 in the infarcted cortex one-day post-stroke." (PMID 38229173, 2024). "Since the knowledge of post-stroke MANF protein expression after cerebral ischemia is limited to acute time-points (24–48 h) and data from human patients is lacking, the initial aim of our study was to characterize the evolution of endogenous MANF protein expression in the ischemic human brain." (PMID 38229173, 2024). "Embarking on the drastic expression transition towards inflammatory cells and the impact of blood-borne inflammation in stroke, we hypothesized that exogenously delivered MANF protein can modulate tissue recovery processes." (PMID 38229173, 2024). "Our findings provide important insight into how endogenous MANF may contribute to post-stroke inflammation, supporting further investigation into MANF-based therapeutic applications." (PMID 38229173, 2024). "Moreover, the microglia field is developing promptly, and new microglia phenotypes have been identified, that remain to be studied in relation to MANF or stroke." (PMID 38229173, 2024). "In addition to its direct actions, MANF was also shown to promote the neuroprotective actions of potential therapeutic agents in stroke." (PMID 37048105, 2023). "Importantly, the deletion of MANF increased the infarct volume in these rats, substantiating the neuroprotective role of MANF in stroke." (PMID 37048105, 2023). "Conceivably, such data are strongly supportive of the notion that serum MANF may be accurately reflective of stroke severity and neurological outcome of human ICH, as well as its determination may be of clinical significance." (PMID 37268902, 2023). "The protective role for MANF in stroke has been studied by several groups." (PMID 37048105, 2023). "MANF was also shown to increase blood flow in the brain regions of stroke models." (PMID 37048105, 2023). "Collectively, stroke robustly increases the expression of MANF in animal models." (PMID 35783104, 2022). "In addition, MANF reversed the stroke-induced upregulation of the innate immunity proteins S100A8 and S100A9, which are highly expressed in phagocytic cells, involved in phagocyte recruitment and released from phagocytes upon activation." (PMID 35783104, 2022). "Further studies should be conducted to explore the molecular mechanisms involved in MANF’s regulation of these processes, which may lead to the development of more efficient therapeutic approaches for patients with stroke." (PMID 35783104, 2022). "The significance and cellular location of MANF in ischemic stroke could also be important to investigate where the inflammatory response is extensive and contribute to the speed of recovery after stroke." (PMID 32757264, 2020). "Furthermore, unbiased RNA screening showed that MANF treatment increased the levels of phagocyte markers, indicating that MANF hastens clearance of cell debris after stroke." (PMID 31044581, 2019). "One interesting hypothesis to consider in this context is whether the immune regulatory effects that MANF has on NSCs, are part of the mechanism involve in recovery from stroke." (PMID 30515104, 2018). "Moreover, since clinical treatment is usually started after the onset of stroke, it is more important to investigate the therapeutic effect of MANF on the injury in reperfusion phase." (PMID 27608005, 2016). "However, the mechanism underlying the upregulation of MANF expression in astrocytes after stroke is not clear, and its mechanism of promotion of neurological recovery needs to be further explored." (PMID 40919080, 2025). "In conclusion, MANF protein expression is induced in activated microglia/macrophage cells in infarcted human and rodent brains, and this could implicate MANF’s involvement in the regulation of post-stroke inflammation in patients and experimental animals." (PMID 38229173, 2024).
Stroke (continued). "When exogenous MANF is administered into the brain before or a few hours after stroke, it has neuroprotective effects on IS models, and the CxxC‐motif is indispensable for the neuroprotective effect of MANF in IS, possibly because of its importance in maintaining MANF's structural conformation." (PMID 39614674, 2024). "Notably, post-stroke MANF administration promotes functional recovery." (PMID 35783104, 2022). "MANF and CD68 positive signals were found to be co-localized in the same cells in the post-stroke rat brain verified by confocal microscopy." (PMID 38229173, 2024). "Although MANF deficiency alone does not induce neuronal loss, MANF deficiency increases neuronal vulnerability, which was shown to manifest when Manffl/fl::NestinCre/+ mice were subjected to such stressors as ethanol, tunicamycin, or blockage of blood flow in the stroke model." (PMID 37555005, 2023). "In our previous study, MANF, a paralogous protein of CDNF, was shown to increase the density of ARG1+ and CD68+ cells in subcortical regions after stroke." (PMID 36792604, 2023). "We found that mutation of the CXXC motif completely abolishes the survival-promoting activity of MANF, both in vitro, in the cultured apoptotic SCG and DRG neurons and in vivo, in the rat model of stroke." (PMID 26720341, 2015). "Our study indicates that after stroke, astrocytes activate PERK and upregulate MANF expression, which inhibits STAT3 phosphorylation, reduces the release of pro-inflammatory cytokines, rescues neuronal synapse loss, and promotes the recovery of neurological function in mice." (PMID 40919080, 2025). "In conclusion, our study demonstrates that after stroke, astrocytes activate PERK and upregulate MANF expression, which inhibits STAT3 phosphorylation, reduces proinflammatory cytokine release, rescues neuronal synapse loss, and promotes the recovery of neurological function in mice." (PMID 40919080, 2025). "On the contrary, in the infarct core we did not observe MANF expression in neurons between 3 days and 2 weeks post-stroke." (PMID 38229173, 2024). "MANF treatment also reduced brain edema and improved falling latency and sensorimotor functions in SAH rats, suggesting that it may improve stroke outcomes." (PMID 37048105, 2023). "In summary, the expression of MANF and XBP1 after stroke has been detected in several time points." (PMID 35783104, 2022). "We overexpressed the MANF protein in the peri-infarct area 2 days after dMCAo by intracerebral AAV7-MANF injection and found improved neurological function already on day 4 and up to day 14 post-stroke." (PMID 35783104, 2022). "Using the same approach of expressing the MANF transgene in the peri-infarct region in the rat dMCAo model, we conducted multiomics to study the effects of peri-infarct-targeted AAV1-MANF administration 2 days post-stroke." (PMID 35783104, 2022). "Besides, upregulation of Mesencephalic Astrocyte-Derived Neurotrophic Factor (MANF) and Cerebral Dopamine Neurotrophic Factor (CDNF) in astrocytes was observed in the experimental model of stroke, which alleviates the damage of endoplasmic reticulum stress." (PMID 34867201, 2021). "A recent report by the same group revealed that post-stroke delivery of MANF to the brain affected immune cell phenotypes, although no clear bias toward anti-inflammatory activation was detected." (PMID 30515104, 2018). "Our data show that the C-terminal RTDL sequence is not required for MANF to protect cortical neurons in a model of stroke." (PMID 26720341, 2015). "The RTDL motif was not needed for the neuroprotective activity of MANF after its extracellular application in the stroke model in vivo." (PMID 26720341, 2015). "Besides, overexpression of MANF induced neural stem cell differentiation, increased cell migration in SVZ explants, activated the STAT3 signaling pathway, and promoted endogenous repair after stroke." (PMID 40919080, 2025).
Stroke (continued). "Interestingly, at 24 h after ischemia, MANF protein expression has been reported also in microglia/macrophages of the ischemic region, but the protein expression of MANF in later post-ischemic timepoints has not been characterized in animal models of stroke." (PMID 38229173, 2024). "No previous studies have reported MANF expression in the human stroke brain." (PMID 38229173, 2024). "However, we were interested in the potential of MANF in acute diagnostics of stroke, but our data do not support the use of free circulating MANF as a potential biomarker in ischemic stroke during the first 2 days after stroke." (PMID 38229173, 2024). "However, recombinant MANF lacking the RTDL sequence was neuroprotective in a rat model of stroke in vivo, suggesting that KDELR binding is not essential for the cytoprotective activity of extracellularly delivered MANF." (PMID 37555005, 2023). "Furthermore, for non-classical neurotrophic factors, mesencephalic astrocyte-derived neurotrophic factor (MANF), together with its homolog cerebral dopamine neurotrophic factor (CDNF), can promote the migration of neural progenitor cells in the stroke model." (PMID 35628525, 2022). "This is unlike similar studies with MANF, where the CXXC motif of MANF was shown to be essential for DmManf functionality and important for the neuroprotective activity of MANF in vitro against ER stress and in an in vivo model of stroke." (PMID 36012764, 2022).
Cerebral ischemia (17 papers, 2012 to 2025). Restriction of arterial blood supply to the brain associated with insufficient oxygenation to support the metabolic requirements of the tissue. "We show that the CXXC motif is critically required for the survival-promoting activity of MANF, as mutation of this motif prevents MANF from being neuroprotective in both types of neurons in vitro and also in the in vivo rat model of cerebral ischemia." (PMID 26720341, 2015). "Consistent with this, early studies demonstrated that MANF rescues cerebral cortex neurons in a rat cerebral ischemia model, and CDNF alleviates damage to astrocytes caused by ER stress." (PMID 25343619, 2014). "Mesencephalic astrocyte-derived neurotrophic factor (MANF) has cytoprotective effects on various injuries, including cerebral ischemia, and it can promote recovery even when delivered intracranially several days after ischemic stroke." (PMID 38229173, 2024). "Mechanistically, RNF2 interacts directly with MANF in nuclear and promotes its monoubiquitination, thereby maintaining the stability of MANF, which confers protection against brain ischemia." (PMID 39614674, 2024). "Mechanistically, we found that RNF2 is an E3 ubiquitin ligase for the mesencephalic astrocyte‐derived neurotrophic factor (MANF), which confers protection against brain ischemia." (PMID 39614674, 2024). "Previous studies have shown that MANF protects against ER stress-induced cell death by regulating UPR-related genes in cerebral ischemia model." (PMID 30760285, 2019). "Previous studies have suggested a secretion-based protective role of MANF in cerebral ischemia and myocardial ischemia." (PMID 30760285, 2019). "After that, the body weight of rats administrated with MANF protein exhibited an increase compared with rats treated only with PBS, which indicates that the MANF protein makes crucial contributions for the therapy of cerebral ischemia/reperfusion injury." (PMID 27608005, 2016). "MANF was significantly upregulated in neurons even by slight cerebral ischemia, suggesting that the neurons are a major source of MANF in the brain tissue." (PMID 23173607, 2012). "We found that severe cerebral ischemia in rats and ER stress inducers in vitro induced MANF expression in astrocytes." (PMID 23173607, 2012). "Various in vitro and in vivo studies have demonstrated that under ER stressed conditions such as cerebral ischemia, hypoxia, and some neurodegenerative diseases, MANF deficiency led to elevated UPR and cell death, while MANF overexpression promoted neuronal survival." (PMID 41339935, 2025). "Furthermore, MANF knockdown effectively abolished the protective effect of RNF2 overexpression after cerebral ischemia." (PMID 39614674, 2024). "Like cerebral ischemia, myocardial ischemia was shown to upregulate MANF protein levels." (PMID 35783104, 2022). "However, the C-terminal arginine-threonine-aspartic acid-leucine (RTDL) sequence of MANF was dispensable for its neuroprotective activity in a model of cerebral ischemia, suggesting alternative mechanisms for exogenous MANF activity." (PMID 34907395, 2022). "MANF expression and protein abundance are increased in the cerebral cortex after brain ischemia." (PMID 32757264, 2020). "MANF is a new member of neurotrophic factor families, which has been shown to be upregulated during ER stress and protected several cell populations from ER stress-induced cell death in vivo or in vitro, especially in PD and cerebral ischemia." (PMID 30760285, 2019). "Indeed, overexpressed MANF has anti-apoptotic effect on the sympathetic and sensory neurons in vitro, and infused MANF protein protects the cerebral cortex in rat model of cerebral ischemia." (PMID 30234112, 2018). "Similarly, MANF mRNA increased after brain ischemia and epileptic insults in the hippocampus and in the cerebral cortex." (PMID 23173607, 2012).
Cerebral ischemia (continued). "Exogenous MANF protects brain tissue from ischemic damage in rat models of ischemic stroke when delivered intracranially as a protein or via viral vector and, more importantly, alleviates functional deficits when injected intracranially several days after cerebral ischemia." (PMID 38229173, 2024). "However, severe cerebral ischemia could induce MANF expression in glial cells, including astrocytes and oligodendrocytes." (PMID 23173607, 2012). "Notably, the apparent unspecificity of these localization patterns suggests that similar uptake mechanisms could likely be seen for the CDNF homolog MANF, and some of them could be involved in the therapeutic effects MANF has in models of PD and cerebral ischemia." (PMID 28275710, 2017). "The objective of the current study was to define the expression of MANF and TREM2 after focal cerebral ischemia and to investigate whether administration of DHA affects MANF and TREM2 expression and neurogenesis and provides additional neuroprotection." (PMID 32757264, 2020). "However, in the rat dMCAo model, the RTDL sequence is not needed for neuroprotection, implying that KDEL receptors do not have a significant role in mediating MANF’s neuroprotective effect on cerebral ischemia." (PMID 35783104, 2022). "However, severe cerebral ischemia could induce RNF2 expression in glial cells, including microglia and astrocytes, but the neurons are still a major source of RNF2, which is similar to the characteristic of MANF expression in the ischemic rat brain." (PMID 39614674, 2024).